LASTR (lncRNA associated with SART3 regulation of splicing)
Synonyms: LINC02657; LINC02677
Gene: Long non-coding RNA gene on chromosome 10 (5,594,980 to 5,635,925, reverse strand). Ensembl gene ENSG00000242147.
Diseases named in the same sentence as LASTR in open-access papers:
LASTR is named in the same sentence as 8 diseases in open-access papers, as found by Europe PMC text mining. Sharing a sentence is not in itself a finding about the gene and the disease. The quoted sentences say what the papers report.
lung carcinoma (5 papers, 2022 to 2024). "The results indicated that LASTR was highly expressed in lung cancer tissue and high expression level was associated with poor clinical features." (PMID 35281858, 2022). "LASTR was highly expressed in lung cancer tissues and cells and high expression level was associated with poor clinical features." (PMID 35281858, 2022). "We verified the difference of LASTR expression in tumor tissues in lung cancer A549 cell line and H1299 cell line." (PMID 38047034, 2023). "RT-PCR was used to verify the high expression of LASTR in LUAD tissues, and the apoptosis of LUAD cell lines was promoted by CCK8 and Transwell experiments to verify the ability of LASTR to promote the migration and invasion of lung cancer cells in vitro." (PMID 38047034, 2023). "Western blotting assay showed that the LASTR/miR-137/TGFA axis modulates activity of the classical PI3K/AKT signaling pathway to promote proliferation of lung cancer cells." (PMID 35281858, 2022). "Cell phenotype experiments indicated that knockdown of LASTR significantly inhibited proliferation and metastatic ability of lung cancer cells." (PMID 35281858, 2022). "The findings of the present study showed that the lncRNA, LASTR plays an oncogene role in lung cancer through miR-137/TGFA/PI3K/AKT axis." (PMID 35281858, 2022). "The findings of the current study showed that the lncRNA, LASTR promotes lung cancer cell progression through a ceRNA mechanism (miR-137/TGFA axis)." (PMID 35281858, 2022). "Knockdown of LASTR considerably curbed the proliferation and metastatic ability of lung cancer cells through the miRNA-137/TGFA axis." (PMID 36249015, 2022). "Cell phenotype experiments were performed using control and LASTR knockdown groups to further explore the biological role of LASTR in lung cancer." (PMID 35281858, 2022). "qRT-PCR results showed that LASTR was highly expressed in lung cancer cell lines relative to the expression level in normal lung epithelial cell line." (PMID 35281858, 2022). "Further analysis showed that miR-137 is a target of LASTR, which can be targeted to inhibit proliferation of lung cancer cells." (PMID 35281858, 2022). "CCK8 assay showed that the control wells had a higher absorbance, indicating that downregulation of LASTR expression decreased the proliferation ability of lung cancer cells." (PMID 35281858, 2022). "For example, it was reported that the expressions of LASTR in lung cancer samples (LUAD and LUSC) were significantly higher than those in neighboring normal tissue." (PMID 36249015, 2022). "This is the first study to explore the role of LASTR in lung cancer." (PMID 35281858, 2022). "Further analysis was conducted to explore whether the lncRNA LASTR promotes lung cancer progression through a ceRNA mechanism (LASTR/miR-137/TGFA axis)." (PMID 35281858, 2022). "LASTR thus modulates PI3K/AKT downstream pathway to affect the regulatory network of lung cancer." (PMID 35281858, 2022). "The findings indicated that miR-137/TGFA is a downstream axis for LASTR activity in lung cancer." (PMID 35281858, 2022). "qRT-PCR results showed that lung cancer cell lines had higher LASTR expression level relative to normal lung epithelial cell lines." (PMID 35281858, 2022). "However, research has demonstrated that LASTR modulates the activity of the U4/U6 recycling factor SART3 to boost cancer fitness, and also modulates the activity of the miR-137/TGFA/PI3K/AKT axis to accelerate lung cancer progression." (PMID 36551318, 2022).
breast carcinoma (4 papers, 2022 to 2023). "The lncRNA LASTR is upregulated in hypoxic breast cancer and increases the fitness of breast cancer cells by regulating the activity of the U4/U6 recycling factor SART3." (PMID 36845400, 2023). "LASTR, upregulated in hypoxic breast cancer, contributes to triple-negative breast cancer cell fitness by regulating the activity of the U4/U6 recycling factor SART3." (PMID 35495133, 2022). "Previous investigations have affirmed that stress-stimulated long non-coding RNA (lncRNA), LINC02657, or LASTR (a lncRNA linked to splicing modulation of SART3), is upregulated in hypoxic breast cancer, a process that is critical for LASTR-positive triple-negative breast tumor." (PMID 38047034, 2023). "Upregulated expression of lncRNA LASTR was found in several epithelial tumors and could facilitate cancer cell fitness in hypoxic breast cancer through SART3." (PMID 36457749, 2022).
gastric cancer (2 papers, 2022 to 2024). A primary or metastatic malignant neoplasm involving the stomach. "The results showed that the expression of LASTR, AL139147.1, AC129507.1, NR2F1−AS1, AL121748.1 and LINC01579 was increased in gastric cancer cell lines relative to GES-1, and AL355574.1, AC020913.1, CDC42−IT1 was decreased in gastric cancer cell lines." (PMID 38546403, 2024).
stomach adenocarcinoma (2 papers, 2022 to 2024). "Interestingly, LASTR has also been used as a ferroptosis-related marker in stomach adenocarcinoma." (PMID 36551318, 2022).
renal carcinoma (1 paper, 2022). A carcinoma arising from the epithelium of the renal parenchyma or the renal pelvis. "It should be emphasized that the specific functions and mechanisms of these three molecules (i.e., FOXD2−AS1, AC026401.3, and LASTR) in renal cancer still require further experimental studies." (PMID 36551318, 2022).
cancer (7 papers, 2021 to 2024). A tumor composed of atypical neoplastic, often pleomorphic cells that invade other tissues. "We discovered that LINC02657 or LASTR (lncRNA linked to SART3 control of splicing), a stress-induced lncRNA, is required for cancer growth." (PMID 38047034, 2023). "Transwell assay results indicated that knockdown of LASTR significantly decreased invasion and migration ability of cancer cells relative to control cells." (PMID 35281858, 2022). "LINC02657 has been named as LASTR (lncRNAassociated with SART3 regulation of splicing), which was reported to decline the fitness of cancer cells by inducing intron retention." (PMID 34196116, 2021).
tumor (4 papers, 2022 to 2024). "Among them, lncRNA associated with SART3 regulation of splicing(LASTR) was confirmed to be highly expressed in GC specimens compared to non-tumor specimens in this cohort." (PMID 36249015, 2022). "The results showed a higher expression level of LASTR in tumor tissue compared with the expression level in corresponding normal tissues." (PMID 35281858, 2022). "In addition to promoting the malignant phenotype of tumors, LASTR also has a potential function in the modulation of the tumor microenvironment, particularly in LUAD." (PMID 38047034, 2023). "Consequently, it was found that the expression of LASTR was distinctly increased in GC specimens compared to non-tumor specimens." (PMID 36249015, 2022).
LASTR also shares sentences with these, for which no sentence is quoted: triple-negative breast carcinoma (1 paper).